PARP2 (poly(ADP-ribose) polymerase 2)
Diseases named in the same sentence as PARP2 in open-access papers (continued):
Sharing a sentence is not in itself a finding about the gene and the disease.
influenza (1 paper, 2019). An acute viral infection of the respiratory tract, occurring in isolated cases, in epidemics, or in pandemics; it is caused by serologically different strains of viruses (influenzaviruses) designated A, B, and C, has a 3-day incubation period, and usually lasts for 3 to 10 days. "The ribonucleotide synthesis enzyme inosine monophosphate dehydrogenase 2 (IMPDH2), a cellular factor that interacts with the PARP1 and PARP2 DDR proteome network, was also required for influenza NP synthesis." (PMID 31015836, 2019). "However, we found that PARP1's role in influenza infection appears to be more complex: inhibition of the PARylation enzymatic activity of PARP1 and PARP2 leads to increased influenza polymerase activity and greater replication of virus in human cells." (PMID 31015836, 2019). "However, influenza infection itself did not alter cellular PARylation, suggesting that the activity of PARP1, PARP2, and other PARP enzymes is not significantly targeted by viral proteins." (PMID 31015836, 2019).
leukemia (1 paper, 2024). A malignant (clonal) hematologic disorder, involving hematopoietic stem cells and characterized by the presence of primitive or atypical myeloid or lymphoid cells in the bone marrow and the blood. "Finally, PARP2 but not PARP1, was found to localize to ALT-associated promyelocytic leukemia bodies (APBs), which are the DNA synthesis centers of ALT cells." (PMID 38565848, 2024).
Lung Tumors (1 paper, 2020). "A significant positive correlation was found between the burden of cigarette smoking as indicated by the variable, pack-years and levels of PARP-2 expression in lung tumors of LC patients with underlying COPD." (PMID 33187221, 2020). "On this basis, we hypothesized that PARP-1 and PARP-2 expression and activity may be increased in lung tumors of patients with COPD." (PMID 33187221, 2020). "Moreover, PARP-2 expression in lung tumor specimens significantly correlated with cigarette smoking burden among LC-COPD patients." (PMID 33187221, 2020). "The LC staging variable did not influence lung tumor PARP-2 expression when all the patients were analyzed as a whole." (PMID 33187221, 2020). "DNA damage, PARP activity, PARP-1 and PARP-2 expression were analyzed in tumor and non-tumor lungs obtained during surgical resection of the lung tumors." (PMID 33187221, 2020). "A decline in PARP-1 and PARP-2 protein expression was seen in lung tumors irrespective of COPD." (PMID 33187221, 2020).
lymph node metastasis (1 paper, 2021). "The higher expression of the PARP2 is significantly correlated with larger tumor size, capsular or vascular invasion, lymph node metastasis, and high histological grade." (PMID 34445986, 2021).
lymphopenia (1 paper, 2017). Reduction in the number of lymphocytes. "These two processes are altered in PARP-1/PARP-2-doubly-deficient proliferating lymphocytes leading to lymphopenia and impaired immune responses." (PMID 28181505, 2017). "Notably, peripheral T-cell lymphopenia in PARP-1/PARP-2 doubly deficient mice results in functional impairment, as revealed by a dramatic defect in the humoral response to the T-dependent antigen TNP-KLH." (PMID 28181505, 2017).
non-alcoholic fatty liver disease (1 paper, 2025). "For example, in non-alcoholic fatty liver disease (NAFLD) and alcoholic fatty liver disease (AFLD), activation of PARP1 and PARP2 leads to increased fat accumulation in hepatocytes, while PARP inhibition attenuates these pathological changes." (PMID 41460301, 2025).
oral cancer (1 paper, 2016). "Although, to our knowledge, no data on PARP2 expression in oral cancer are available, this is pointing towards a less important role of PARP2 in tumorigenesis and a low suitability as cancer imaging agent compared to PARP133." (PMID 26900125, 2016).
ovarian tumors (1 paper, 2023). "Rucaparib is a well-known inhibitor of PARP-1, PARP-2, and PARP-3 enzymes that is clinically used for the treatment of certain types of ovarian tumors." (PMID 36768904, 2023).
pancreatic cancers (1 paper, 2025). "The PARP1 and PARP2 biology observed for the CRC cases in this study differs significantly from their established status in breast, ovarian, prostate and pancreatic cancers." (PMID 40573300, 2025).
sarcopenia (1 paper, 2020). Progressive decline in muscle mass due to aging which results in decreased functional capacity of muscles. "Furthermore, autophagy was implicated in muscular differentiation and sarcopenia, making it likely that the silencing of PARP2 may affect the differentiation of C2C12 cells." (PMID 32046043, 2020).
Stroke (1 paper, 2021). Sudden impairment of blood flow to a part of the brain due to occlusion or rupture of an artery to the brain. "The large protection seen in PARP2−/− mice was unexpected because PARP2 is less abundant than PARP1, suggesting a complex interaction between PARP1 and PARP2 in the context of stroke." (PMID 34025565, 2021). "Eight studies have used PARP1-null mice (PARP1−/−) and PARP2-null mice (PARP2−/−) to investigate the role of PARPs in stroke with models of MCAO." (PMID 34025565, 2021).
T-cell lymphomas (1 paper, 2017). "Moreover, double-deficiency in PARP-1/PARP-2 in T-cells led to highly aggressive T-cell lymphomas with long latency." (PMID 28181505, 2017).
Zinc deficiency (1 paper, 2019). A deficiency of the essential metal Zinc; an essential cofactor for many enzymes. "Among the four genes, only PARP2 (At4g02390) exhibited a difference between the wild type and rpt5a-4 under zinc deficiency." (PMID 31249317, 2019). "In PARP2, induction by zinc deficiency was evident in rpt5a-4 but not significant in the wild type." (PMID 31249317, 2019).
cancer (71 papers, 2010 to 2026). A tumor composed of atypical neoplastic, often pleomorphic cells that invade other tissues. "Working by inhibiting PARP enzymes, particularly PARP1 and PARP2; this inhibition causes an accumulation of DNA damage in cancer cells, leading to cell cycle arrest and apoptosis (cell death)." (PMID 41510186, 2026). "PARP1/PARP2 inhibitors have emerged as effective drugs for the treatment of cancers with BRCA deficiencies." (PMID 39684238, 2024). "In particular, PARP1- and PARP2-specific inhibitors are being used in combination with conventional anticancer drugs to promote synthetic lethality in cancer cells with BRCA1/2 mutations." (PMID 35269974, 2022). "The important message from this development is that therapeutic benefit has been increased more by identifying new susceptible cancer targets for existing PARP1/PARP2 inhibitors than by developing novel, improved inhibitors." (PMID 34210965, 2021). "Overall, these initial studies suggest that effective PARGi-induced cancer cell targeting requires a cell treatment or cellular genetic background that predisposes to enhanced PARP1/PARP2 activation." (PMID 34806016, 2021). "Indeed, the initial designation of these compounds to BRCA1/BRCA2-mutated cancers already stemmed from the discovery of the synthetic lethal relationship between PARP1/PARP2 inhibition and faulty HR machinery." (PMID 34210965, 2021). "Together, our findings suggest that PARP1/2 dual inhibitors may increase cancer bone metastasis through PARP2-dependent regulation of IMCs, and cause bone loss through PARP1/2-dependent regulation of osteoclasts." (PMID 32221289, 2020). "Here, the authors show that PARP1/2 dual inhibitors may increase cancer bone metastasis through PARP2-dependent regulation of immature myeloid cells, and cause bone loss through PARP1/2-dependent regulation of osteoclasts." (PMID 32221289, 2020). "Therefore, it has been hypothesized that selectively inhibiting PARP1 would reduce PARPi toxicity associated with PARP2 inhibition while improving synthetic lethality in HRD cancers and subsequently improving the efficacy of PARPi treatments." (PMID 40521389, 2025). "This suggests that a correct dosage of HPF1 is important for proper balancing of various PARP1- and PARP2-catalysed reactions, and therefore subtler changes beyond simple loss-of-function might also be of therapeutic relevance in both cancer and other diseases." (PMID 34210965, 2021). "This is consistent with the role of PARP2 in DNA repair; since genomic instability and mutation is a hallmark of cancer, the cancer-specific co-expression of PARP2 and cell cycle genes may indicate that PARP2 is actively engaged in DNA repair while cancer cells divide." (PMID 30532070, 2019). "Several next-generation PARPis exhibited improved PARP1 selectivity over PARP2, resulting in lower hematological toxicity while demonstrating greater therapeutic efficacy in multiple cancer models." (PMID 40521389, 2025). "These drugs preferentially block the ability of PARP1 and PARP2 to initiate repair of DNA damage and selectively kill cancer cells that are unable to repair double strand breaks based on the concept of synthetic lethality." (PMID 40021124, 2025). "Poly (ADP-ribose) polymerase (PARP) inhibitors (PARPi) targeting PARP1 and PARP2 have revolutionized cancer therapy by selectively killing cancer cells with defective DNA repair." (PMID 40021124, 2025). "Although PARP2 plays a role in the repair system by detecting DNA breaks and recruiting repair factors, the PARP2 protein promotes proliferation and invasion in cancers like prostate cancer." (PMID 40739397, 2025). "Poly(ADP-ribose)polymerase 2 (PARP2) is a nuclear protein, DNA damage sensor and an emerging target for development of anti-cancer drugs." (PMID 40586906, 2025). "The lncPTTG3P/miR-383/PARP2 axis was reported to play a part in cancer cell invasion and migration in HCC." (PMID 39408693, 2024).
cancer (continued). "While an initial study reported an induction of bone metastasis with PARPi, being mainly mediated by PARP-2 in the myeloid lineage and less by PARP-2 in cancer cells, this study administered PARPi first for one week prior to the injection of cancer cells." (PMID 39201718, 2024). "The role of PARP1 and PARP2 in the DNA damage response underscores the potential of targeting these pathways in cancer therapy, particularly in the context of BRCA-deficient cancers." (PMID 38111536, 2023). "PARP1 and PARP2 have been extensively studied and well characterized for their role in DNA damage repair and cancer progression." (PMID 36814782, 2023). "Through the analysis of tumor tissues in the database, PARP-2 was found in a range of cancer tissues, including those from HCC patients." (PMID 35466317, 2022). "Rucaparib (RCP) is a potent selective inhibitor of both PARP-1 and PARP-2 enzymes that induces synthetic lethality in cancer cells." (PMID 35236893, 2022). "Olaparib, which specifically inhibits PARP1 and PARP2 and thus is used for cancer therapy, also significantly suppressed cell proliferation at 5 μM and 10 μM." (PMID 35447104, 2022). "Olaparib is an FDA-approved dual PARP-1 (IC50 = 0.005 μM) and PARP-2 (IC50 = 0.001 μM) inhibitor for the treatment of cancer." (PMID 36304149, 2022). "This treatment modality takes advantage of the dependence of homologous recombination-deficient cancer cells on PARP1 and PARP2 for the repair of endogenous DNA lesions." (PMID 33922595, 2021). "PARP1 and PARP2 have been extensively studied for their roles in DNA repair and as targets for cancer therapeutics." (PMID 35096828, 2021). "ASA-A, ASA-B, ASA-C and POPA generated a statistically significant enhancement and increase of the PARP1 and PARP2 mRNA expression in all tested cancer cell lines." (PMID 34440232, 2021). "Recently, cellular ADPr levels have been proposed as a biomarker that positively correlates with PARP1/PARP2 inhibitor sensitivity across certain types of cancer cells." (PMID 34210965, 2021). "The overlapping roles of PARP1 and PARP2 in DNA damage response (DDR) and the fact that most PARPis target both enzymes suggest that PARP2 also contributes to PARPi-induced cancer cell death." (PMID 33922595, 2021). "This is supported by studies reporting limited tumor growth of PARP-1/PARP-2 proficient cancer cell lines in PARP-1 or PARP-2 knockout host mice." (PMID 33923319, 2021). "BRCA1-null UWB1.289 cancer cells transcribe a significantly higher PARP2 (t-test, p < 0.001) and a strikingly lower PARP1 mRNA content (t-test, p < 0.001) due to the BRCA1 loss of activity." (PMID 34440232, 2021). "Several PARP1 and PARP2 inhibitors are currently employed in the clinic or undergoing trials for treatment of various cancers." (PMID 34210965, 2021). "Accordingly, elucidating the distinct regulatory roles of CSB in SSBR-mediated by PARP1 and PARP2 might uncover novel cancer therapeutic strategies that maximize PARPis’ efficacy with reduced toxicity to improve patient outcomes in cancer treatment." (PMID 39996712, 2025). "Hence, targeting the BER pathway—specifically PARP1 and PARP2—forms the basis for the “synthetic lethality” mechanism that the PARP inhibition strategy utilizes for the treatment of those cancer subsets with HRD." (PMID 40573300, 2025). "Therefore, PARP1 and PARP2 inhibition provides cancer-targeted potency by disrupting the DNA repair processes in cancer cells." (PMID 38099989, 2024). "It has been suggested that the PARP2 function is not essential for antitumor activity in HRR-deficient cancer models, and that only PARP1 inhibition is required." (PMID 36994441, 2023). "Dual-inhibitors of PARP1 and PARP2 are promising anti-cancer drugs." (PMID 35349716, 2022). "As YHP-836 showed enzymatic inhibitory activity against PARP1 and PARP2, we investigated if YHP-836 could suppress cancer cell proliferation with BRCA mutations via synthetic lethality." (PMID 35910366, 2022).
cancer (continued). "To evaluate whether FOXM1 is a valuable target, we analyzed the differential expression of FOXM1, PARP1, and PARP2 between cancer tissues and adjacent normal tissues in 31 cancers from the TCGA projects." (PMID 34880209, 2021). "While PARP1 is clearly involved in all ten cancer hallmarks, an increasing body of evidence supports the role of other PARPs in modifying these cancer hallmarks (e.g., PARP5a and 5b in replicative immortality and PARP2 in cancer metabolism)." (PMID 33922595, 2021). "So, though PARP inhibitors may result side effects, it also can make cancer cured by targeting PARP2." (PMID 33486472, 2021). "In addition to impairing DNA repair, PARP1/PARP2 inhibitors—which are in clinical use against a growing list of cancers—trap the abundant PARP1 protein on DNA breaks, which has genotoxic cytotoxic consequences, especially in BRCA1- or BRCA2-deficient cancers." (PMID 34210965, 2021). "Moreover, the metabolic and autophagy-promoting roles of PARP2 are likely to affect cancer cell sensitivity to DNA-damaging agents." (PMID 33922595, 2021). "We first examined the individual roles of PARP1 and PARP2 in cancer cells." (PMID 32221289, 2020). "Understanding the immunomodulatory roles of PARP-1 and PARP-2 may provide invaluable clues to the rational development of more selective PARP-centered therapies which target both the cancer and its microenvironment." (PMID 32046278, 2020). "It is now emerging that PARP-1 and PARP-2 may not only impact cancer cell biology, but also modulate the anti-tumor immune response." (PMID 32046278, 2020). "Poly (ADP-ribose) polymerase (PARP)-1 and PARP-2 are key players in cancer." (PMID 33187221, 2020). "It is possible that while the inhibition of PARP1 by PARP inhibitors may provide therapeutic efficacy in cancer, the simultaneous inhibition of PARP2 may result in toxicity via transcriptional dysregulation in normal tissues." (PMID 29259170, 2017). "As there are multiple agents on the market that inhibit paralogues, such as trametinib (MEK1, MEK2) and PARP inhibitors (PARP1, PARP2), each of the 27 gene pairs we identified could be considered as targets for therapy development if follow-up studies can identify selectivity for cancer cells." (PMID 33637726, 2021). "Understanding the immunomodulatory roles of PARP-1 and PARP-2 may provide invaluable clues for the rational development and exploitation of more selective anti-cancer PARP inhibitor drugs, both as new monotherapeutic approaches and in combinations with immunotherapy." (PMID 32046278, 2020). "Furthermore, the ability of olaparib to exacerbate bone metastasis of Py8119 cells in WT mice was completely abolished in PARP2CKO mice, pinpointing that olaparib-induced bone metastasis is predominantly mediated by PARP2 in the myeloid lineage and less by PARP2 in the cancer cells." (PMID 32221289, 2020). "As a logical continuation to this list, the silencing of PARP2 supported the differentiation of myoblasts to myofibers, at least in part, through the modulation of autophagy and, in line with that, the depletion of PARP2 was protective against cancer cachexia and muscle wasting." (PMID 32046043, 2020). "Related to the synthetic lethal DNA damage elicited in homologous recombination-defective cancer cells, many clinical PARPi can trap PARP1 and PARP2 on DNA as part of their anticancer mechanism of action." (PMID 40021124, 2025). "The development of poly (ADP-ribose) polymerase inhibitors (PARPi) represents a novel approach to cancer treatment, targeting PARP1, PARP2, and PARP3 proteins crucial in repairing single-strand DNA breaks." (PMID 38910707, 2024). "Finally, our findings identified a specific function of PARP2 at telomeres in conditions of replication stress that corroborates an already reported unique role of this enzyme in mitigating genomic replication in cancer cells undergoing replication stress-driven oncogene dysregulation." (PMID 38565848, 2024).